SH2D2A (SH2 domain containing 2A)
Description:
Could be a T-cell-specific adapter protein involved in the control of T-cell activation. May play a role in the CD4-p56-LCK-dependent signal transduction pathway. Could also play an important role in normal and pathological angiogenesis. Could be an adapter protein that facilitates and regulates interaction of KDR with effector proteins important to endothelial cell survival and proliferation.
Synonyms: TSAd; VRAP; F2771
Tractability: PROTAC: ubiquitination databases record sites on it; its protein half-life has been measured.
Gene: Protein-coding gene on chromosome 1 (156,806,235 to 156,817,014, reverse strand). Ensembl gene ENSG00000027869.
Subcellular location: Cytoplasm
Pathways (Reactome):
Signal Transduction: VEGFA-VEGFR2 Pathway
Gene Ontology:
Molecular function: protein binding; protein-macromolecule adaptor activity
Biological process: signal transduction; T cell activation
Cellular component: cytoplasm; cytosol
Genetic constraint (gnomAD): Loss-of-function variants: 26 observed, 33.65 expected, observed/expected ratio (o/e) 0.77, 90% interval 0.56 to 1.07. The upper end of that interval is the gene's LOEUF score, 1.07, which puts it in group 4 of 6, group 1 being the genes least tolerant of losing a copy. Missense variants: 430 observed, 406.72 expected, observed/expected ratio (o/e) 1.06, 90% interval 0.98 to 1.14. Synonymous variants: 182 observed, 161.92 expected, observed/expected ratio (o/e) 1.12, 90% interval 1 to 1.27.
Homologues: Orthologues: macaque SH2D2A (93% identical), chimpanzee SH2D2A (92% identical), dog SH2D2A (77% identical), pig SH2D2A (76% identical), mouse Sh2d2a (61% identical), guinea pig SH2D2A (58% identical), rat Sh2d2a (56% identical), tropical clawed frog sh2d2a (29% identical), Caenorhabditis elegans F13B12.6 (13% identical). Paralogues in human: SH2D7 (20% identical), HSH2D (18% identical), SH2D4B (13% identical), SH2D4A (12% identical).
Diseases named in the same sentence as SH2D2A in open-access papers:
SH2D2A is named in the same sentence as 22 diseases in open-access papers, as found by Europe PMC text mining. Sharing a sentence is not in itself a finding about the gene and the disease. The quoted sentences say what the papers report.
myeloma (3 papers, 2012 to 2025). "Here we report that SH2D2A-deficient TCR-transgenic mice display increased resistance towards transplanted myeloma." (PMID 23144743, 2012). "We thus tested whether SH2D2A-deficient mice were still resistant towards myeloma when larger inoculums of myeloma cells were used." (PMID 23144743, 2012). "To explore the effect of SH2D2A deficiency in a more physiological context we used a well-characterized TCR-transgenic model for CD4+ T cell mediated resistance to the MOPC315 mouse myeloma." (PMID 23144743, 2012). "SH2D2A was upregulated in T cells that infiltrated ovarian and renal cancers and multiple myeloma, but was downregulated in T cells infiltrating breast cancers, supporting an inverse mechanistic role for SH2D2A dependent on tumor type." (PMID 41394860, 2025). "The observation that Id-specific TCR-transgenic mice were more resistant to myeloma in the absence than in the presence of SH2D2A could be due to altered vascular function, as SH2D2A is also expressed in endothelial cells." (PMID 23144743, 2012). "Normal non-transgenic BALB/c mice as well as wild type and SH2D2A-deficient Id-specific TCR-transgenic mice were injected subcutaneously with a high dose of MOPC315 myeloma cells (2×106 cells)." (PMID 23144743, 2012). "The SH2D2A-deficient, Id-specific TCR-transgenic mice allowed us to study T cell responses triggered by the cognate peptide in vitro, as well as T cell mediated resistance to transplanted myeloma in vivo." (PMID 23144743, 2012). "Wild type and SH2D2A-deficient Id-specific TCR-transgenic mice as well as wild-type and SH2D2A-deficient non-TCR transgenic BALB/c mice were injected s.c. with a low dose of MOPC315 myeloma cells (0,16×106 cells)." (PMID 23144743, 2012). "Although the phenotypes of BALB/c mice as well as Id-specific TCR-transgenic BALB/c mice were not considerably affected by the lack of SH2D2A, the SH2D2A-deficient Id-specific TCR-transgenic mice displayed improved protection towards MOPC315 myeloma." (PMID 23144743, 2012). "All non-transgenic BALB/c mice, independent of SH2D2A, developed s.c. myelomas." (PMID 23144743, 2012). "Taken together, in the absence of SH2D2A, TCR-transgenic mice are better protected from transplanted myeloma, which correlates with reduced central deletion of tumor-specific SP CD4+ thymocytes in tumor-free mice." (PMID 23144743, 2012). "When challenged with myeloma cells, Id-specific TCR-transgenic BALB/c mice lacking SH2D2A displayed increased resistance towards tumor development." (PMID 23144743, 2012).
fibrosarcoma (1 paper, 2012). A malignant mesenchymal fibroblastic neoplasm affecting the soft tissue and bone. "In the T241 fibrosarcoma tumor model, SH2D2A-deficient C57BL/6 mice develop smaller tumors as a result of reduced angiogenesis." (PMID 23144743, 2012).
heart failure (1 paper, 2025). Inability of the heart to pump blood at an adequate rate to meet tissue metabolic requirements. "Dysfunction in SH2D2A may elevate the risk of AKI in the context of heart failure, underscoring the necessity to investigate its mechanisms for the development of targeted therapeutic interventions." (PMID 40124680, 2025).
infiltrating ductal carcinoma (1 paper, 2022). "However, except for HSD11B1 and SH2D2A in infiltrating ductal carcinoma, other MDGs did not have statistically significant clinical outcome, possibly due to small sample size." (PMID 35844785, 2022).
malignant mesothelioma (1 paper, 2020). A malignant neoplasm of the pleura or peritoneum, arising from mesothelial cells. "Using whole exome sequencing of five WDPMs of the peritoneum, we have identified distinct mutations in EHD1, ATM, FBXO10, SH2D2A, CDH5, MAGED1, and TP73 shared by WDPM cases but not reported in malignant mesotheliomas." (PMID 32545767, 2020). "Mutations in FBXO10, SH2D2A, and TP73 has not been reported in any malignant mesotheliomas." (PMID 32545767, 2020).
tumor (11 papers, 2012 to 2025). "Tumor free TCR-transgenic SH2D2A-deficient mice had higher numbers of Id-specific single positive CD4+ thymocytes compared to TCR-transgenic wild-type mice." (PMID 23144743, 2012). "Nonetheless, SH2D2A-deficient Id-specific TCR-transgenic BALB/c mice displayed increased resistance towards a B cell derived tumor." (PMID 23144743, 2012). "All wild type BALB/c mice, 55 % (6 out of 11) wild type Id-specific TCR-transgenic mice and 47 % (7 out of 15) SH2D2A-deficient Id-specific TCR-transgenic were sacrificed due to large tumor burden (>1 cm3)." (PMID 23144743, 2012). "It is thus less likely that the increased tumor protection observed in SH2D2A-deficient mice can be explained by more efficient IFN-γ production by the Id-specific CD4+ T cells." (PMID 23144743, 2012). "M315 serum levels measured on day 21 and 35 after tumor cell injection, were significantly lower in SH2D2A-deficient compared to wild type Id-specific TCR-transgenic mice." (PMID 23144743, 2012). "In summary, SH2D2A-deficiency led to increased tumor resistance of Id-specific TCR-transgenic mice also when they were challenged with tolerizing amounts of tumor cells." (PMID 23144743, 2012). "This indicates that SH2D2A deficient cells are less susceptible to the tolerizing effect of a large tumor inoculum." (PMID 23144743, 2012). "However TCR transgenic SH2D2A-deficient peripheral CD4+ T cells in tumor mice displayed higher CD69 surface expression compared to mice without tumor (p = 0.05) or unchallenged mice (p<0,007)." (PMID 23144743, 2012). "Thus, SH2D2A-deficiency resulted in increased tumor resistance in Id-specific TCR-transgenic mice." (PMID 23144743, 2012). "Gene sets related to T cell activation were more strongly expressed in SH2D2A-expressing T cells (compared to SH2D2A-negative cells) that infiltrated the 3D-tumor model." (PMID 41394860, 2025). "Gene sets associated with T cell exhaustion were also upregulated in 3D-tumor infiltrating SH2D2A-expressing cells." (PMID 41394860, 2025). "Differentially expression of SH2D2A in tumor-infiltrated T cells vs. T cells found in the blood from the same patient from 21 different solid tumor entities." (PMID 41394860, 2025). "Taken together, our single-cell RNA expression analysis affirmed that SELPLG and SH2D2A are differentially regulated in single tumor-infiltrating L1CAM-CAR T cells, suggesting a functional role, while TIAM2, CORO1B and MYH10 do not seem to influence L1CAM-CAR T cell migration." (PMID 41394860, 2025). "We analyzed whether SH2D2A was also upregulated in tumor-infiltrating T cells in this dataset." (PMID 41394860, 2025). "The results showed that the expression of SH2D2A and TERF2IP genes was significantly upregulated in the tumor tissues, whereas the expression of TMSB4X, although also elevated, was not statistically different." (PMID 37842637, 2023). "In our investigation, we substantiated the heightened expression levels of SH2D2A and TERF2IP in tumor tissues based on our analysis of clinical surgical resection samples." (PMID 37842637, 2023). "Downregulation of DUSP1 suppresses the expression of angiogenic factors, such as SH2D2A and VEGF-C in non-small-cell lung cancer (NSCLC) cells, and functional assays have confirmed the role of DUSP1 in promoting tumor angiogenesis." (PMID 24409315, 2014). "The improved tumor resistance observed in SH2D2A-deficient Id-specific TCR-transgenic mice could thus be due to alteration in Lck activity mimicking reduced Lck levels, which results in persistence of effector T cells and improved tumor response as described by Caserta and colleagues." (PMID 23144743, 2012). "Expression analysis of key regulators of cell migration (CXCR3, CCR7, CXCR5 and ITGAL, which encodes LFA1, an alias protein name) within these groups revealed significant upregulation of CCR7 in a subset of tumor-infiltrating SH2D2A-positive T cells and CXCR3 in infiltrating SH2D2A-positive T cells." (PMID 41394860, 2025).
tumor (continued). "Manipulating L1CAM-CAR T cells with CRISPR/Cas9 to knock out SELPLG expression or enhance SH2D2A expression did not affect CAR T cell functions necessary for anti-tumor activity in vitro." (PMID 41394860, 2025). "Tumor-infiltrating L1CAM-CAR T cells expressed lower levels of the selectin P ligand (SELPLG) glycoprotein and higher levels of the T cell-specific adaptor protein, SH2D2A." (PMID 41394860, 2025). "In the presence of tumor, mice lacking SH2D2A showed a similar pattern of thymic tolerance induction as wild type mice." (PMID 23144743, 2012). "The reduced number of TCR-transgenic SP CD4+ thymocytes and reduced percentage of peripheral CD4+ T cells (data not shown) in mice with tumor compared to tumor-free mice, independent of SH2D2A expression, is consistent with these previous results." (PMID 23144743, 2012). "Collectively, our data imply that overexpressing SH2D2A does not interfere with L1CAM-CAR T cell mechanisms used to recognize and kill tumor cells." (PMID 41394860, 2025). "The expression levels of SH2D2A, TERF2IP, and TMSB4X were significantly different between normal and tumor samples of TCGA, while other model genes were not significantly different." (PMID 37842637, 2023). "The results showed that the expression of SH2D2A and GATA2 were upregulated (P = .0067 and P = .6021, respectively), while CXCL8, LIF, and VASH2 were downregulated in IVL tumor samples compared to nontumor tissue (P = .9281, P = .5406 and P = .0625, respectively)." (PMID 32372565, 2020). "However, in the absence of SH2D2A, the numbers of GB113+ CD4+ SP thymocytes of tumor resistant mice were significantly higher than in the wild type mice." (PMID 23144743, 2012). "Since we did not observe any major effect of SH2D2A on the in vitro responses of naïve TCR-transgenic CD4+ T cells, while there clearly was a difference in tumor protection, we examined whether presence of SH2D2A affected the in vitro response of TCR-transgenic CD4+ T from tumor-experienced mice." (PMID 23144743, 2012).
cancer (5 papers, 2012 to 2025). A tumor composed of atypical neoplastic, often pleomorphic cells that invade other tissues. "To investigate the role of TSAd in CD4+ T cell mediated cancer immunosurveillance, we crossed SH2D2A-deficient mice with idiotype (Id)-specific TCR-transgenic mice." (PMID 23144743, 2012). "KDR, SH2D2A, SRC, and KRAS were included in the VEGF signaling pathway, of which variants were associated with cancer recurrence when they were assessed simultaneously." (PMID 34599262, 2021). "SH2D2A plays an important modulatory role in T-cell mediated immune surveillance of cancer and may lead to defective control and elimination of autoreactive T cells." (PMID 31993418, 2019). "Our results suggest a modulatory role for SH2D2A in T cell mediated immune surveillance of cancer." (PMID 23144743, 2012). "Further studies are required to determine whether targeting SH2D2A function in T cells may be a potential adjuvant in cancer immunotherapy." (PMID 23144743, 2012). "Results from a GeneMANIA database analysis showed that PLCG2, CHI3L2, SH2D2A, and NLRP3 and 20 other proteins formed a complex network of which 12 genes were enriched in cancer-related pathways." (PMID 31993418, 2019).
infection (5 papers, 2015 to 2021). The state of being infected such as from the introduction of a foreign agent such as serum, vaccine, antigenic substance or organism. "This detailed understanding of MCMV and its interaction with NK and CD8+ T cells together with availability of Sh2d2a−/− mice provide ideal tools for investigating the function of TSAd in the context of infection." (PMID 25783199, 2015).
retinopathy (2 papers, 2020 to 2025). "To assess the role of these downstream players in retinopathy, we expanded our studies using mice treated with tamoxifen at P12 to specifically delete TSAd expression in endothelial cells, Sh2d2afl/fl; Cdh5-CreERT2 (denoted Sh2d2a iECKO)." (PMID 32312382, 2020).
brain diseases (1 paper, 2022). "In addition, DIP2A was associated with abnormal brain development and brain diseases, and SH2D2A was important for proper activation of T-cells." (PMID 35865544, 2022).
SH2D2A also shares sentences with these, for which no sentence is quoted: autoimmune disease (2 papers); breast carcinoma (2); bladder cancer (1); hematologic malignancies (1); hypothyroidism (1); leprosy (1); lupus- (1); multiple myeloma (1); neuroblastoma (1); neurodegenerative disease (1); renal carcinoma (1); virus infection (1).